ATP6V1B2 (ATPase H+ transporting V1 subunit B2)
Description:
Non-catalytic subunit of the V1 complex of vacuolar(H+)- ATPase (V-ATPase), a multisubunit enzyme composed of a peripheral complex (V1) that hydrolyzes ATP and a membrane integral complex (V0) that translocates protons. V-ATPase is responsible for acidifying and maintaining the pH of intracellular compartments and in some cell types, is targeted to the plasma membrane, where it promotes acidification of the extracellular environment. The V-ATPase complex also acts as an activator for mTORC1 on lysosomal membrane by promoting the guanine nucleotide exchange factor (GEF) of the Ragulator complex, thereby enabling mTORC1 recruitment. In renal intercalated cells, can partially compensate the lack of ATP6V1B1 and mediate secretion of protons (H+) into the urine under base-line conditions but not in conditions of acid load (By similarity).
Synonyms: ATP6B2; VPP3; VATB; Vma2; HO57; ATP6B1B2; DOOD; ZLS2
Tractability: Small molecule: a structure with a bound ligand is known. Antibody: UniProt places it where antibodies can reach, with high confidence; its Gene Ontology location is reachable by antibodies, with medium confidence. PROTAC: ubiquitination databases record sites on it; its protein half-life has been measured; a small molecule that binds it is known.
Target class: Enzyme; Hydrolase
Gene: Protein-coding gene on chromosome 8 (20,197,381 to 20,230,399, forward strand). Ensembl gene ENSG00000147416.
Subcellular location: Apical cell membrane; Melanosome; Cytoplasm; Cytoplasmic vesicle, secretory vesicle, synaptic vesicle membrane; Cytoplasmic vesicle, clathrin-coated vesicle membrane
Subcellular location (Human Protein Atlas): Vesicles
Pathways (Reactome):
Transport of small molecules: Ion channel transport; Transferrin endocytosis and recycling
Cellular responses to stimuli: Amino acids regulate mTORC1
Developmental Biology: Regulation of MITF-M-dependent genes involved in lysosome biogenesis and autophagy
Immune System: ROS and RNS production in phagocytes
Signal Transduction: Insulin receptor recycling
Gene Ontology:
Molecular function: protein binding; proton transmembrane transporter activity; proton-transporting ATPase activity, rotational mechanism; ATP binding
Biological process: proton transmembrane transport; regulation of macroautophagy; vacuolar acidification; ATP metabolic process; synaptic vesicle lumen acidification
Cellular component: apical plasma membrane; extracellular exosome; lysosomal membrane; melanosome; vacuolar proton-transporting V-type ATPase, V1 domain; cytoplasm; cytosol; plasma membrane; clathrin-coated vesicle membrane; extrinsic component of synaptic vesicle membrane; microvillus; proton-transporting V-type ATPase, V1 domain; ruffle; synaptic vesicle membrane
Genetic constraint (gnomAD): Loss-of-function variants: 19 observed, 61.02 expected, observed/expected ratio (o/e) 0.31, 90% interval 0.22 to 0.46. The upper end of that interval is the gene's LOEUF score, 0.46, which puts it in group 2 of 6, group 1 being the genes least tolerant of losing a copy. Missense variants: 461 observed, 635.56 expected, observed/expected ratio (o/e) 0.73, 90% interval 0.67 to 0.78. Synonymous variants: 273 observed, 232.91 expected, observed/expected ratio (o/e) 1.17, 90% interval 1.06 to 1.3.
Homologues: Orthologues: chimpanzee ATP6V1B2 (100% identical), mouse Atp6v1b2 (99% identical), pig ATP6V1B2 (99% identical), rat Atp6v1b2 (99% identical), rabbit ATP6V1B2 (99% identical), dog ATP6V1B2 (99% identical), guinea pig ATP6V1B2 (98% identical), macaque ATP6V1B2 (96% identical), zebrafish atp6v1b2 (93% identical), tropical clawed frog atp6v1b2 (92% identical), Drosophila melanogaster Vha55 (86% identical), Caenorhabditis elegans vha-12 (81% identical), and 1 more. Paralogues in human: ATP6V1B1 (85% identical), ATP5F1B (26% identical), ATP6V1A (26% identical), ATP5F1A (25% identical).
Diseases named in the same sentence as ATP6V1B2 in open-access papers:
ATP6V1B2 is named in the same sentence as 40 diseases in open-access papers, as found by Europe PMC text mining. Sharing a sentence is not in itself a finding about the gene and the disease. The quoted sentences say what the papers report.
deafness (7 papers, 2019 to 2025). An inherited or acquired condition characterized by the complete loss of the ability to hear from one or both ears. "The variants in the ATP6V1B2 gene have been reported in deafness–onychodystrophy syndrome, and we identified a novel variant (c.1303A>G, p.M435V) in one case." (PMID 39336818, 2024). "Notably, ATP6V1B2 has recently been linked to severe epileptic encephalopathy and deafness, onychodystrophy, osteodystrophy, mental retardation, and seizures syndrome, suggesting the malformation in bAVMs as an extension of ATP6V1B2-related disorders." (PMID 36139398, 2022). "Pathogenic variants of ATP6V1B2 have been associated with various epileptogenic phenotypes, including intellectual disability (ID), seizures, and/or DOORS syndrome (deafness, onychodystrophy, osteodystrophy, ID, and seizures)." (PMID 36980356, 2023). "The autosomal dominant ATP6V1B2 p.Arg506* variant can cause both congenital deafness with onychodystrophy, autosomal dominant (DDOD) and deafness, onychodystrophy, osteodystrophy, mental retardation, and seizures syndromes (DOORS)." (PMID 37628590, 2023). "DOORS [deafness, onychodystrophy, osteodystrophy, intellectual disability (mental retardation), and seizures] syndrome can be caused by mutations in the TBC1D24 and ATP6V1B2 genes, both of which are involved in endolysosomal function." (PMID 32849222, 2020).
onychodystrophy (7 papers, 2020 to 2025). "ATP6V1B2 is associated with Congenital deafness associated with onychodystrophy." (PMID 35177665, 2022).
COVID-19 (5 papers, 2021 to 2024). A disease caused by infection with severe acute respiratory syndrome coronavirus 2. "In accordance with the PPI analyses, we found that the V-ATPase subunit ATP6V1B2, the c-MYC co-activator TRRAP, and the cohesin complex subunit SMC3 were associated with the COVID-19 patient hospitalization, suggesting their clinical relevance to disease." (PMID 38168026, 2024). "This phenomenon reflects the discussions in the Introduction that RIPK3 is related to the natural essence of COVID-19, while ATP6V1B2, IFI27, BTN3A1, SERTAD4, and EPSTI1 contain more information about SARS-CoV-2." (PMID 36298522, 2022). "The mono-CD16+ cell population in COVID-19 patients showed reduced transcription levels of genes related to lysine degradation (NSD1, KMT2E, and SETD2) and elevated transcription levels of genes involved in OXPHOS (ATP6V1B2, ATP5A1, ATP5E, and ATP5B), which may inhibit M2-like polarization." (PMID 33936072, 2021).
depression (3 papers, 2016 to 2024). "Polymorphisms in mitochondrial genes such as TOMM40, ATP6V1B2, and MOA are correlated to depression in humans." (PMID 38800537, 2024). "Importantly, a single nucleotide polymorphism (SNP) within ATP6V1B2, rs1106634, has exhibited a suggestive p-value in a meta-analysis in schizophrenia and bipolar disorder (p = 3.97 × 10−6) and has been associated with lifetime risk of depression (p < 0.001) in a recent study." (PMID 34880450, 2022). "The main finding of our study is supporting the role of the ATP6V1B2 rs1106634 A allele, implicated in depression GWAS-s with a suggestive significance, as a risk allele for lifetime but not current depression suggesting a role in the long-term development of affective illness." (PMID 27824360, 2016).
DOORS syndrome (3 papers, 2021 to 2024). DOORS syndrome (also known as DOOR syndrome) is a multiple congenital anomalies-intellectual disability syndrome characterized by sensorineural hearing loss (deafness), onychodystrophy, osteodystrophy, mild to profound intellectual disability, and seizures. "In humans, a recurrent truncating variant in ATP6V1B2 has been associated with DOORS syndrome." (PMID 39273013, 2024). "Interestingly, the clinical phenotype of TBC1D24 biallelic variants may overlap with that of ATP6V1B2 mutations, as both genes represent the major genetic cause of DOORS syndrome, implying a physiological link between TBC1D24 and v-ATPase function." (PMID 39273013, 2024). "However, the underlying mechanism of how the c.1516C>T variant of ATP6V1B2 causes DDOD or DOORS syndrome remains unknown." (PMID 34912366, 2021).
hearing loss (3 papers, 2021 to 2025). "This study establishes a novel therapeutic paradigm for ATP6V1B2‐associated hearing loss and vestibular dysfunction, with significant clinical potential." (PMID 40068100, 2025). "This study provides significant insights into the pathophysiological mechanisms underlying ATP6V1B2‐associated hearing loss in vivo." (PMID 40068100, 2025). "Our findings expand the variant spectrum of hearing-loss-associated genes and provide new insights on understanding of hearing-loss candidate genes ATP6V1B2, TJP2, and KIF11." (PMID 34912366, 2021). "Our findings expand variant spectrums of hearing loss candidate genes, and shed new insights of pathogenetic effects of ATP6V1B2, TJP2, and KIF11 on hearing functions." (PMID 34912366, 2021). "Effective therapies for ATP6V1B2‐associated hearing loss remain elusive." (PMID 40068100, 2025). "Patients with ATP6V1B2-related syndromes showed severe congenital sensorineural hearing loss, which was not consistent with the milder hearing phenotype of Atp6v1b2Arg506*/Arg506*mice despite the presence of the same type of mutation." (PMID 34746137, 2021).
Intellectual disability (3 papers, 2020 to 2026). "Pathogenic variants in ATP6V1B2, which encodes a critical subunit of vacuolar-type H+-ATPases (V-ATPases), disrupt lysosomal acidification via haploinsufficiency and clinically manifest as intellectual disability and seizure disorders." (PMID 41896517, 2026).
chordoma (2 papers, 2021 to 2025). Chordomas are rare malignant tumors arising from embryonic remnants of the notochord in axial skeleton. "ATP6V1B2 was among the genes that were considered as both super-enhancer-associated and essential for chordoma cell viability." (PMID 34070849, 2021).
DDOD syndrome (2 papers, 2021 to 2025). "Previously, we developed a knockin mouse model carrying the Atp6v1b2 c.1516C>T (p.Arg506*) variant, the most common pathogenic variant identified in patients with DDOD syndrome." (PMID 40068100, 2025). "To further investigate interventions for Atp6v1b2‐associated hearing loss, we established a hair cell‐specific conditional knockout mouse model (Atp6v1b2fl/f;Atoh1Cre/+) that accurately recapitulates the congenital severe to profound hearing loss phenotype seen in DDOD syndrome patients." (PMID 40068100, 2025). "In 2014, our group identified ATP6V1B2 as the gene responsible for DDOD syndrome and provided evidence supporting haploinsufficiency as the underlying genetic mechanism." (PMID 40068100, 2025). "The cause of DDOD syndrome (MIM: 220500) was first identified, from three unrelated cases, to be a de novo heterozygous variant (c.1516C>T; p.R506*) in the ATP6V1B2 gene (MIM: 606939)." (PMID 34912366, 2021).
epilepsy (2 papers, 2023 to 2026). A brain disorder characterized by episodes of abnormally increased neuronal discharge resulting in transient episodes of sensory or motor neurological dysfunction, or psychic dysfunction. "Many genes encoding subunits of V-ATPases, namely ATP6V0C, ATP6V1A, ATP6V0A1, and ATP6V1B2, have been associated with neurodevelopmental disorders and epilepsy." (PMID 37628590, 2023). "It would be interesting to know if individuals with the p.R506* variant, or any other deleterious variant in the ATP6V1B2 gene, are more prone to other types of induced epilepsy or seizures caused by trauma, encephalitis, infections, or fever for example." (PMID 37628590, 2023). "Our results confirm that variants in ATP6V1B2 can cause seizures and that the Atp6v1b2emR506* heterozygous mouse model is a valuable tool to further explore the pathophysiology and potential treatments for vacuolar ATPases-associated epilepsy and disorders." (PMID 37628590, 2023).
Obesity (2 papers, 2025). Accumulation of substantial excess body fat. "Moreover, genes involved in lysosomal biogenesis and phagocytosis including Atp6v1b2, Atp6v0d2, Lipa, and Lamp2 were also reported to be induced in the ATMs in obesity." (PMID 40244655, 2025).
schizophrenia (2 papers, 2022 to 2025). A major psychotic disorder characterized by abnormalities in the perception or expression of reality. "In schizophrenia, abnormal miR-92 expression and reduced glutamatergic synapses have been reported, while BBB disruption and altered ATP6V1B2 (the human homolog of Vha55) expression are also observed." (PMID 41008637, 2025).
asthma (1 paper, 2026). "In this study, we integrated a house dust mite (HDM)-induced asthma model with quantitative lactylomics to identify ATP6V1B2, a key V-ATPase subunit, as a core lactylation target." (PMID 41637881, 2026).
attention deficit-hyperactivity disorder (1 paper, 2024). A disorder characterized by a marked pattern of inattention and/or hyperactivity-impulsivity that is inconsistent with developmental level and clearly interferes with functioning in at least two settings (e.g. at home and at school). "For example, male-specific pQTL rs3213946 is also eQTL for several genes (ITGAV, FAM171B, ATP6V1B2 and ZC3H15) and associated with diseases such as inflammatory bowel disease, coronary artery disease, and attention deficit hyperactivity disorder." (PMID 38326779, 2024).
candidiasis (1 paper, 2021). Infection with the organism Candida. "Interestingly, we showed that genetic variation in close vicinity of the phagocytosis/phagosome maturation-associated genes ASGR2, LAMP1, RAB42, GEM, ATP6V1B2, and RAB20 are associated with susceptibility to candidiasis." (PMID 33510868, 2021).
Cognitive impairment (1 paper, 2020). Abnormal cognition is characterized by deficits in thinking, reasoning, or remembering. "Pyridoxine deficiency causes cognitive impairments and reduction in 5-HT and DA levels, which may be associated with a reduction of ATP6V1B2 and elevation of HSC70 levels in the hippocampus." (PMID 32344819, 2020). "Atp6v1b2 knock-in mice show cognitive defects in passive avoidance and novel object recognition tests and the ATP6V1B2 rs1106634 A allele is a risk factor in hippocampal cognitive deficits." (PMID 32344819, 2020).
colon cancer (1 paper, 2023). "In another example, patients with colon cancer that harbor deletions of the ATP6V1B2 locus (component of vacuolar ATPase) with activation of genes involved in mitochondrion organization (GO: 0007005; MSigDB26) had favorable prognosis." (PMID 36950380, 2023).
E. coli infection (1 paper, 2023). "Further qRT-PCR assays showed that representative genes of phagosome maturation were significantly upregulated in response to E. coli infection including ATP6V1A, ATP6V1B2, BF2, CTSS, and TFRC, while COLEC12 was downregulated at 72 h." (PMID 36411420, 2023).
influenza (1 paper, 2011). An acute viral infection of the respiratory tract, occurring in isolated cases, in epidemics, or in pandemics; it is caused by serologically different strains of viruses (influenzaviruses) designated A, B, and C, has a 3-day incubation period, and usually lasts for 3 to 10 days. "In cells depleted of a subunit of the vATPase (ATP6V1B2) responsible for acidification of endosomes, and CAS (CSE1L), a factor required for nuclear import of influenza vRNPs, infection was almost completely inhibited." (PMID 22046129, 2011).
osteopetrosis (1 paper, 2019). Osteopetrosis, also known as marble bone disease, is a descriptive term that refers to a group of rare, heritable disorders of the skeleton characterized by increased bone density on radiographs. "Genetic studies implicate a critical role for subunits ATP6V1B2, ATP6V1C1, ATPV0D2, and ATP6V0A3 (TCIRG1) in osteoclast activity as relevant mutations lead to osteopetrosis." (PMID 30804932, 2019).
Salmonella Infections (1 paper, 2019). Infections with bacteria of the genus SALMONELLA. "Given the role of V-type proton ATPase in phagosomal maturation, it is likely that the re-routing of phagosomal maturation process in Salmonella infection is mediated through an ATP6V1B2 dependent process and is likely to include cross-talks between the pathogen’s flagella biosynthesis and T3SS." (PMID 31881845, 2019).
tauopathies (1 paper, 2025). "Interestingly, recent study demonstrated the ability of phosphorylated tau to disrupt V-type proton ATPase function through its interaction with the ATP6V1B2 subunit, which was associated with phospho-tau lesions in all 4 studied tauopathies." (PMID 40082954, 2025).
infection (5 papers, 2011 to 2025). The state of being infected such as from the introduction of a foreign agent such as serum, vaccine, antigenic substance or organism. "Regarding the oxidative phosphorylation genes analyzed, Ndufa1 and ATP6v1b2 displayed the reported kinetics, characterized by an initial decrease of expression during days 3 and 4 post infection, followed by an increase during the recovery phase." (PMID 37679643, 2023).
cancer (3 papers, 2020 to 2023). A tumor composed of atypical neoplastic, often pleomorphic cells that invade other tissues. "Similar to RNA-seq and qRT-PCR data, immunoblot analysis further confirmed the upregulation of ATP6V0D1 and ATP6V1B2 in cells cultured in suspension compared to the attached cancer cells." (PMID 34234852, 2021). "Importantly, blocking STAT3 signaling in cancer cells inhibited the expression of two members of the V-ATPase family - ATP6V1B2 and ATP6V0D1." (PMID 34234852, 2021). "In addition, in TCGA pan-cancer dataset, although the PBP signature overall was not prognostic, the higher expression levels of individual signature gene members, such as GBP5 and ATP6V1B2, were associated with better disease-specific survival." (PMID 37587913, 2023).
genetic disease (2 papers, 2021 to 2025). "Together, this is the first demonstration that ATP6V1B2-caused DDOD is an autosomal dominant genetic disease, compared to previous cases with de novo mutation." (PMID 34912366, 2021).
neurodevelopmental disorder (2 papers, 2021 to 2023). A behavioral and cognitive disorder with onset during the developmental period that involves impaired or aberrant development of intellectual, motor, or social functions. "Indeed, variants in human ATP6V1B2 that are predicted to alter interactions within the V1 complex cause dominantly-inherited neurodevelopmental disorders." (PMID 33340069, 2021).
psychiatric disorder (1 paper, 2025). A disorder characterized by behavioral and/or psychological abnormalities, often accompanied by physical symptoms. "Several genes—including ATP6V1B2, FBXO7, PHF23, and WDR6—consistently emerged as risk factors in multiple conditions, suggesting that dysregulation of autophagy-related or immune-modulatory pathways may contribute broadly to the development of inflammatory and psychiatric disorders." (PMID 41595424, 2025).
ATP6V1B2 also shares sentences with these, for which no sentence is quoted: and epileptic encephalopathy (2 papers); Seizure (2); Alzheimer disease (1); bipolar disorder (1); chronic asthma (1); coronary artery disease (1); developmental and epileptic encephalopathy (1); encephalitis (1); inflammatory bowel disease (1); joint disease (1); pigmented villonodular synovitis (1); vestibular disorder (1); Zimmermann-Laband syndrome (1).